KRAS (KRas proto-oncogene, GTPase)
Diseases named in the same sentence as KRAS in open-access papers (continued):
Sharing a sentence is not in itself a finding about the gene and the disease.
lung cancer (continued). "The HRAS and KRAS oncogene mutations are well defined, however, the clinical significance of RAS expressions in non–small-cell lung cancer (NSCLC) is still uncertain." (PMID 33549031, 2021). "It was also eminent that SMARCA4 plays a role in growth and tumorigenicity of KRAS-driven lung cancers by supporting the oncogenic transcriptional signaling landscape of the tumor." (PMID 34440689, 2021). "We began our study of the role of BLT2 in KRAS-mutant lung cancer by examining the basal expression levels of BLT2, 5-LOX, and 12-LOX in KRAS-mutant lung cancer cells." (PMID 34635780, 2021). "To further analyze the role of elevated BLT2 expression in KRAS-driven lung cancer, we performed a co-staining experiment in lung tissues by IF analysis." (PMID 34635780, 2021). "Whereas STK11/LKB1 loss alone was not sufficient to trigger oncogenesis, STK11 inactivation in a mutant KRAS-driven model of mouse lung cancer strongly stimulated growth and metastasis." (PMID 34831355, 2021). "Among KRAS mutant lung cancer cell lines, KRAS G12D preferentially activates MAPK signaling, while KRAS G12C or G12V mutants activate Ral signaling and exhibit decreased growth factor-dependent activation of the PI3K pathway." (PMID 34680229, 2021). "IL22 also plays an essential role in KRAS-mutant lung cancer by inducing an inflammatory tumor microenvironment and protects lung cancer cell stemness." (PMID 34944848, 2021). "Lung cancer with oncogenic KRAS makes up a significant proportion of lung cancers and is accompanied by a poor prognosis." (PMID 33830081, 2021). "In the current study, we administered two well-studied mitochondria-targeted antioxidants, MitoQ and MitoTEMPO, to mice with BRAF-induced malignant melanoma and KRAS-induced lung cancer, and defined their impact on tumor progression and metastasis." (PMID 33499262, 2021). "Previous work from our laboratory demonstrated that epithelial subpopulations of mutant KRAS lung cancers are responsive to MEK inhibitors while mesenchymal cells within the tumors are resistant." (PMID 33972557, 2021). "It was demonstrated that STK11/LKB1 downregulates CPS1 transcription via AMPK-mediated effects and that KRAS/STK11 mutant lung cancer cells upregulate expression of CPS1, allowing cell division and tumor development." (PMID 34831355, 2021). "In conclusion, our data showed the clear effects of verteporfin as a therapeutic modality in KRAS-mutant lung cancer cells." (PMID 33830081, 2021). "In conclusion, to our knowledge, this report is the first to define the role of BLT2 in KRAS-driven lung cancer." (PMID 34635780, 2021). "Another reason for the aggressive behavior and difficulty in treating KRAS-mutant lung cancer is its highly inflammatory phenotype." (PMID 33809660, 2021). "Since KRAS-mutant NSCLC is smoking-related lung cancer, high T cell infiltration and high TMB are usually observed in smokers with KRAS mutations." (PMID 34012925, 2021). "Based on our previous work that demonstrated JQ1 sensitivity across different genetic subsets of LAC, we focused on EGFR and KRAS mutant cell lines as these represent the major driver genes in this type of lung cancer." (PMID 33712563, 2021). "In one study, highly specific intramolecular epitope spreading was partly responsible for preventative effects of a vaccine against KRAS-induced lung cancer." (PMID 33869008, 2021).
lung cancer (continued). "Pulmonary LELC had better prognosis, and previous studies also have discovered that classic lung cancer oncogenic drivers including KRAS, EGFR, BRAF, ALK, and ROS1 were limitedly involved in tumorigenesis and progression of pulmonary LELC." (PMID 34221995, 2021). "The direct relationship between p-eIF2α and p-ERK also became evident in a different mouse lung cancer model, which was driven by KRAS Q61R/L after urethane (ethyl carbamate) treatment." (PMID 34330898, 2021). "Here, we evaluated the immunomodulatory effects of F+D in vitro and in vivo using the novel syngeneic KRAS+ murine lung cancer model, FVBW-17, derived from a lung adenocarcinoma induced by exposure of an FVB/N mouse to the tobacco carcinogen NNK." (PMID 35008514, 2021). "Our study portrays the adaptive PERK/p-eIF2α branch of ISR as an essential component of tumorigenesis and a valid target of therapeutic intervention for mutant KRAS lung cancer treatment." (PMID 34330898, 2021). "The oncogenic mutation of tumour-inducing genes, such as KRAS and EGFR or their surrogates, is prevalent in human lung cancers." (PMID 34381028, 2021). "Lung cancer is often driven by molecular alterations, such as EGFR and KRAS mutations, and ALK rearrangements expressed in tumor tissues of patients with NSCLC." (PMID 34722241, 2021). "Here, we identified verteporfin, which is a known YAP1 inhibitor, as a striking therapeutic candidate for KRAS-mutant lung cancer cells involving the unresolved ER stress mechanisms." (PMID 33830081, 2021). "Recently, exciting data of activity have been reported with KRASG12C inhibitors in early-phase clinical trials, raising a growing interest for KRAS inhibition, especially in lung cancer." (PMID 33777798, 2021). "Recent studies indicate co-dependence signaling by SHOC2 signaling in either KRAS mutant or EGFR mutant lung cancer cells." (PMID 34102455, 2021). "In this study, drug screening in KRAS-mutant lung cancer cells identified verteporfin as a specific therapeutic candidate." (PMID 33830081, 2021). "For this purpose HCT-116 (CRC), NCI-H358 cells (lung cancer) were used, where the KRAS expression was shown to be significantly decreased at RNA and at protein levels." (PMID 34781949, 2021). "This team used single-cell sequencing of three KRAS-G12C-mutant lung cancer lines treated with ARS1620 for variable lengths of time." (PMID 34200676, 2021). "Accumulating studies have proven that lung cancers harboring oncogenic alterations in ROS1 or EML4-ALK respond poorly to immunotherapy, whereas KRAS mutations are associated with an improved response to immunotherapy." (PMID 34497760, 2021). "In our study, a series of pathways, including the TGF-β pathway, were enriched between SDPR-low and SDPR-high specimens in KRAS mutant lung cancers." (PMID 33435990, 2021). "Our previous research highlighted the reliance of KRAS-mutant epithelial-like lung cancer cells with high miR-200 expression on activated MAPK signaling pathway and increased susceptibility to MEK inhibitors." (PMID 34309585, 2021). "Recent studies have indicated the inconsistent effects of RNA interference and small-molecule inhibition on oncogenic KRAS-driven lung cancer cells." (PMID 33830081, 2021). "Few studies have systematically evaluated the relationship between the mutation status of EGFR, KRAS, and PIK3CA and lung cancer patients, especially among patients with different types of lung cancer." (PMID 34217313, 2021). "Consistent with previous reports, our data showed its inhibitory effects on cell proliferation in KRAS-mutant lung cancer cells." (PMID 33830081, 2021). "Investigations with two additional PDXs derived from primary KRAS‐mutant lung cancer cells (PF563, PF139) had similar results." (PMID 34369083, 2021).
lung cancer (continued). "Lung cancer, especially NSCLC, has particularly high somatic mutations, including mutations in KRAS, EGFR and other surrogates, which share similar outputs at the downstream end of their signalling pathways." (PMID 34381028, 2021). "We measured the cell viability, which is represented by z score, and determined the difference in cell viability between KRAS-mutant lung cancer cells and WT cells." (PMID 33830081, 2021). "With a previously published protocol, we sought to identify a specific inhibitor of KRAS-mutant lung cancer cells and assessed drug sensitivity by small-molecule screening." (PMID 33830081, 2021). "Compared with traditional siRNA-based drugs, the amiRNA-KD2 was able to discriminate KRAS G12S and WT lung cancer cells while retaining the ability to exert favorable effects on proliferation, migration, and necrosis." (PMID 33803619, 2021). "Understanding resistance mechanisms to targeted therapies and immune checkpoint blockade in mutant KRAS lung cancers is critical to developing novel combination therapies and improving patient survival." (PMID 33972557, 2021). "To identify the SDPR expression level in mouse and human lung tissues and tumors, we established KRAS-oncogene-driven lung cancer models and detected SDPR expression using RT-qPCR." (PMID 33435990, 2021). "FGFR1 inhibition combined with the MEK inhibitor trametinib has shown to mediate cell death in KRAS-mutant lung cancer both in vitro and in vivo." (PMID 33777798, 2021). "In the present study, we identified that YAP/TAZ expressions were upregulated in KRAS-mutant lung cancer cells." (PMID 34073318, 2021). "Systematic screening with a chemical-based approach has produced a therapeutic candidate in KRAS-mutant lung cancer cells." (PMID 33830081, 2021). "Treatments with ISR inhibitors, including a memory-enhancing drug with limited toxicity, provides a suitable therapeutic option for KRAS-driven lung cancer insofar as they substantially reduce tumor growth and prolong mouse survival." (PMID 34330898, 2021). "In contrast, high-level KRAS and loss of LKB1 leads to significantly decreased overall survival in lung cancer." (PMID 33514834, 2021). "A study on 110 patients evaluated if MR radiomics from brain metastasis originated from lung cancer was shown to associate with EGFR, ALK and KRAS mutations and reported excellent model performances for all three tissue biomarkers (AUC > 0.9, LOOCV)." (PMID 34208595, 2021). "Mice vaccinated either prophylactically or therapeutically with such conjugates demonstrated impaired tumour growth in KRAS-mutant lung cancer models." (PMID 34200676, 2021). "Nevertheless, studies have shown that the combination of conventional chemotherapy with inhibitors of MEK, B-cell lymphoma-extra large (BCL-XL), and phosphoinositide 3-kinase is a promising method for the prevention and treatment of KRAS-mutant lung cancer." (PMID 32530390, 2021). "Our extended in silico analysis that includes 189 lung cancer cell lines and patient samples revealed only a weak correlation between CDA expression levels and KRAS mutational status." (PMID 33874986, 2021). "In this study, we demonstrated that the 5-/12-LOX-BLT2 cascade is highly amplified during KRAS-driven lung cancer progression." (PMID 34635780, 2021). "Activation of STAT3 in MDSCs led to induction of Tregs, DC inhibition and macrophage polarization towards the pro-tumorigenic M2 subtype in a KRAS lung cancer model." (PMID 33917037, 2021).
lung cancer (continued). "We investigated how culture supernatants of the human lung carcinoma cell lines NCI-H226, an NSCLC cell line with wild-type RAS, or NCI-H2122, a KRAS-mutated cell line, affect the maturation and cytokine secretion of LPS-stimulated moDCs." (PMID 34671021, 2021). "For instance, the co-activation of KRAS and Myc in lung cancer drives the recruitment of anti-inflammatory macrophages by CCL9 and IL-23 and exclusion of T, B cells and NK cells." (PMID 33116132, 2020). "The antioxidant supplementation of N-acetyl cysteine and vitamin E mimics the NRF2-HMOX-1 action, leading to the BACH1 stabilization and glycolysis induction in KRAS-mutant lung cancer." (PMID 33228209, 2020). "The KRAS-mutant lung cancer are more common in Western population (26%), but in Asia population only 11%." (PMID 32244355, 2020). "While the development of novel therapeutics for KRAS-driven NSCLC is undeniably critical, rexinoids should be tested in lung cancer models harboring different mutations found in human lung cancer." (PMID 33335263, 2020). "This study aimed to systematically profile the alterations and sex- and age-related differences in the drug metabolizing enzymes (DMEs) in a KRAS-mutant mouse model of lung cancer (KRAS mice)." (PMID 33240601, 2020). "The driver mutations in lung cancer are gene mutations in EGFR and KRAS proto-oncogene (KRAS), ALK rearrangements, and altered MET proto-oncogene (MET) signaling." (PMID 32219066, 2020). "Overall, these results suggest that the MiR181ab1 cluster is required for maintenance of the oncogenic phenotype in KRAS-driven human non–small cell lung cancer." (PMID 31874105, 2020). "Conversely, let-7 inhibits cellular proliferation by negatively regulating the KRAS oncogene in lung cancer." (PMID 33233641, 2020). "EZH2 was also highly expressed in lung cancers with positive KRAS expression, and the correlation was positive in lung adenocarcinoma (r = 0.3129 and p < 0.001)." (PMID 33299862, 2020). "In lung cancer, the genetic ablation of Tregs in mutant KRAS transgenic mice developed fewer lung tumours, indicating that Tregs are required in lung tumourigenesis." (PMID 33116132, 2020). "For instance, PD-L1 expression in KRAS-mutant lung cancer cell lines is regulated by MAPK-dependant transcriptional activity of AP-1 and partially by STAT359." (PMID 33116132, 2020). "A recent study of young patients with nonsmall cell lung cancer showed that higher frequency of ALK and HER2 genetic alterations were associated with young age, while, mutations in KRAS, STK11, and EGFR exon 20 are more common in older patients." (PMID 32657049, 2020). "Although KD efficiency should be improved as only a 50% decrease in PIERCE1 expression was observed, siRNA-mediated PIERCE1 KD suppressed tumor growth in KRAS-mutant lung cancer." (PMID 32728173, 2020). "Lung cancer is well established as a highly heterogeneous tumor that harbors various gene alterations including mutations in EGFR, KRAS, BRAF, PD-L1, and PIK3CA, as well as ALK rearrangement and HER2 amplification." (PMID 33411683, 2020). "Nonetheless, IKKα’s role in KRAS-induced lung cancer remains controversial, as a second report claims that IKKα acts as a tumour suppressor and that IKKα genetic deletion actually promotes KRAS-induced lung cancer." (PMID 32823550, 2020). "Furthermore, the KRAS G12C mutation might be a drug target in early stage lung cancer." (PMID 32607238, 2020). "Previously, oncogenic KRAS was described as regulator of ASNS induction by ATF4 in lung cancer models." (PMID 33214553, 2020). "Because a previous report indicated that MEK inhibition activated STAT3 signaling in KRAS-mutant lung cancer cells, we examined the activation of STAT3 signaling." (PMID 31124056, 2020).
lung cancer (continued). "Targeting this kinase in NSCLC has therefore been proposed as a therapeutic strategy in KRAS-mutant lung cancer that is resistant to conventional and targeted therapies." (PMID 32104498, 2020). "MAPK and AKT pathways govern crucial physiological processes, such as proliferation and survival, in KRAS-mutant lung cancer." (PMID 32728173, 2020). "A combination of the TRAIL and Smac mimic (allows overcoming KRAS-induced survival in cancer cells) was shown to induce strong apoptosis in premalignant lung adenoma cells and inhibit the formation of KRAS-induced lung cancer in vivo." (PMID 32429547, 2020). "Despite the promising results achieved with direct KRAS G12C inhibitors, approximately half of the G12C-mutant lung cancer patients show only a partial response to these therapeutic agents." (PMID 32548736, 2020). "Accordingly, adding mTOR and IGF1R inhibitors to ARS-1620 greatly improves its effectiveness on KRAS G12C-mutant lung cancer cells in vitro and in mouse models." (PMID 32548736, 2020). "Collectively, these data suggest that PIERCE1 inhibition provides clinical benefit particularly for mutant KRAS-driven lung cancer." (PMID 32728173, 2020). "Taken together, these data suggest that PIERCE1 is involved in the proliferation of KRAS-mutant lung cancer cells." (PMID 32728173, 2020). "Upregulation of both miR181a and miR181b in wild-type KRAS lung cancer cells was observed upon expression of oncogenic KRAS." (PMID 31874105, 2020). "Through gene sequencing, it can be seen that lung cancer-related genes such as epidermal growth factor receptor gene mutation, c-MET, ROS1, KRAS, and BRAF, play an extremely important role in diagnosis and treatment of lung cancer." (PMID 32316985, 2020). "Long-term smoking is well-known to be the main cause of lung cancer, while environmental effects (e.g., air pollution and particulate matters) and genetic variations (e.g., KRAS and EGFR mutations) can also cause lung cancer." (PMID 33233641, 2020). "Trametinib is an MEK1 inhibitor for treating EML4-ALK-positive, EGFR-activated, and KRAS-mutant lung cancers." (PMID 32245216, 2020). "Our stapled P2short peptide thus constitutes an attractive means of sensitizing CDK4 to ATP-competitive therapeutics for the treatment of KRAS-mutant lung cancer patients." (PMID 32104498, 2020). "Mechanistically, PIERCE1 depletion inhibits cell growth and AKT phosphorylation (pAKT) at S473, which is particularly observed in KRAS-mutant lung cancers." (PMID 32728173, 2020). "In our study, a KRAS-mutant mouse model of lung cancer (KRAS mice, spontaneous tumors in the lung) was used to study the changes in DMEs in the development of lung cancer." (PMID 33240601, 2020).